HMGB1 (high mobility group box 1)
Diseases named in the same sentence as HMGB1 in open-access papers (continued):
Sharing a sentence is not in itself a finding about the gene and the disease.
cystitis (5 papers, 2016 to 2024). Inflammation of the urinary bladder. "LMWH also prevents endogenous HMGB1-dependent pain, including cystitis-related bladder pain and neuropathic pain, caused by surgical injury of the spinal nerve." (PMID 33396481, 2020). "We have demonstrated that the activation of RAGE by HMGB1 derived from unknown cells plays a role in the development of the bladder pain accompanying CPA-induced cystitis in mice." (PMID 32707767, 2020). "Collectively, we propose hypothetical mechanisms of cystitis-related bladder pain in CPA-treated mice, which involve a neuroimmune crosstalk mediated by ATP and HMGB1." (PMID 32707767, 2020). "High Mobility Group Box-1 (HMGB1), a chromatin-binding protein, mediates bladder pain (but not inflammation) in an experimental model (cyclophosphamide) of cystitis." (PMID 27010488, 2016). "We conducted an immunofluorescence analysis to measure the expression of endogenous TLR4 ligand HMGB1, and glial activation markers GFAP and IBA1 in lumbar spinal cords, and found that HMGB1, GFAP and IBA1 were downregulated after TAK‐242 injection in the group with cystitis." (PMID 38415918, 2024). "Thus, as does the HMGB1/RAGE pathway, the CSE/H2S/Cav3.2 pathway is considered to participate in the bladder pain accompanying CPA-induced cystitis in mice." (PMID 32707767, 2020). "Given NF-κB is a major downstream signal of RAGE activation, in the present study, we wished to understand whether the CSE/H2S/Cav3.2 pathway could be downstream of the HMGB1/RAGE pathway, in the development of bladder pain, accompanying the CPA-evoked cystitis." (PMID 32707767, 2020).
delirium (5 papers, 2016 to 2025). A disorder characterized by confusion; inattentiveness; disorientation; illusions; hallucinations; agitation; and in some instances autonomic nervous system overactivity. "A relationship between delirium and circulating HMGB1 requires further investigation." (PMID 29669581, 2018). "The authors explain that although HMGB1 levels increase on the first postoperative day, failure to capture the true peak of HMGB1 may prevent an accurate assessment of its relationship with delirium." (PMID 39857699, 2025). "This explains why an increase in HMGB1 levels was observed without a significant correlation with delirium severity." (PMID 39857699, 2025). "However, some clinical studies have pointed out that although HMGB1 levels increase on the first postoperative day, this increase is not significantly correlated with the severity of delirium." (PMID 39857699, 2025). "Second, since our study calculated the sample size based on the change in HMGB1 levels, it may not have been sufficient to show a difference in the incidence of delirium in our study due to the small sample size." (PMID 37892748, 2023). "We also evaluated human plasma levels of HMGB1 from patients diagnosed with POD on day 3 and found a significant elevation compared to age-matched surgical subjects without delirium (627.1 ± 160.2 vs. 1418 ± 258.4, p < 0.05)." (PMID 27822212, 2016).
dilated cardiomyopathy (5 papers, 2018 to 2023). Cardiomyopathy which is characterized by dilation and contractile dysfunction of the left and right ventricles. "Clinical studies have shown that HMGB1 and its associated inflammatory cytokines (IL-6, TNF-α) may be involved in the pathophysiological processes of dilated cardiomyopathy and accelerated heart function decline." (PMID 35571117, 2022).
dry eye (5 papers, 2017 to 2025). "Current research indicates that HMGB1 plays an important role in activating ocular surface inflammatory factors, and it can stimulate downstream signaling pathways, which is key to dry eye formation." (PMID 41210848, 2025). "Again, HMGB1 was also found to be increased in the tears of patients with dry eye syndrome compared to those of healthy patients." (PMID 37446230, 2023). "First, we looked at the effect of anti-HMGB1 treatment on the clinical manifestations of dry eye in NOD.B10.H2b mice." (PMID 28837629, 2017). "In conclusion, subconjunctival administration of anti-HMGB1 improved the clinical manifestations of dry eye in NOD.B10.H2b mice, although the anti-HMGB1 treatment did not affect B or plasma cells." (PMID 28837629, 2017). "This study indicates that subconjunctival administration of anti-HMGB1 attenuates the clinical manifestations of dry eye." (PMID 28837629, 2017). "Nevertheless, to our knowledge, this is the first study to report an improvement in dry eye after anti-HMGB1 treatment and to propose a possible role for ILC3s in this mouse model." (PMID 28837629, 2017). "This study shows that subconjunctival administration of anti-HMGB1 attenuates clinical manifestations of dry eye." (PMID 28837629, 2017). "The increase in ILC3 cells in the draining lymph nodes and the increased IL-22 expression in the intraorbital glands after anti-HMGB1 treatment suggest a possible role for ILC3s in the improvement of dry eye in this model." (PMID 28837629, 2017). "In addition, neutralizing HMGB1 antibodies have been reported to alleviate xerostomia and xerophthalmia in mouse models." (PMID 35250993, 2022). "Furthermore, it has been shown that HMGB1 can exhibit proinflammatory role during ocular surface damage and dry eye-related inflammation via interacting with soluble PAMPs and binding to TLRs." (PMID 35096875, 2021). "This could explain why blocking HMGB1 improves dry eye, although the exact redox status of cysteine is not known." (PMID 28837629, 2017). "Though HMGB1 expression was found to be enhanced by dry eye conditions, the crosstalk between DUOX2-mediated excessive ROS release and HMGB1 during DED inflammation progression has not been previously investigated." (PMID 35096875, 2021).
eosinophilia (5 papers, 2017 to 2023). "Intriguingly, airway overexpression of mmu-miR-30a-3p suppressed Runx2 and Hmgb1 expression, and alleviated airway eosinophilia in a mouse model of allergic airway inflammation." (PMID 35093061, 2022). "There was a positive correlations between sputum HMGB1 expressions in sputum eosinophilia and sputum TNF-a, IL-5 and IL-13 levels." (PMID 28630596, 2017). "Anti-HMGB1 and anti-IL-33 treatment of IRF7-/- mice decreased ILC2 numbers in the lung, type-2 cytokine responses in BALF, and airway eosinophilia." (PMID 32658914, 2020). "Interestingly, an airway increases in mmu-miRNA-30a-3p inhibited HMGB1 and RUNX2 expression and reduced airway eosinophilia in an experimental animal model." (PMID 36675299, 2023). "This study confirmed that sputum HMGB1 expression was higher in asthmatics than in healthy controls; sputum HMGB1 expression was significantly higher in subjects with sputum eosinophilia than in subjects without sputum eosinophilia." (PMID 28630596, 2017). "Serum total HMGB1 was not significantly elevated in patients with nevirapine‐induced SJS/TEN (3·98 ± 2·17 ng mL−1), MPE (3·92 ± 2·75 ng mL−1) or drug reaction with eosinophilia and systemic symptoms (4·73 ± 3·00 ng mL−1) vs. tolerant controls (2·97 ± 3·00 ng mL−1)." (PMID 30613954, 2019).
hematoma (5 papers, 2010 to 2024). A hematoma is a collection of blood from a vascular structure into an extravascular space. "In the present study, we observed that high mobility group box-1 (HMGB1) decreased in the injured brain area beneath the epidural hematoma (EDH) in rats, concurrent with elevated plasma levels of HMGB1." (PMID 38892076, 2024). "We detected the effects of choline diet on the relative expression of P38 MAPK, MyD88, HMGB1, and IL-1β around the hematoma with western blot analysis at 24 h after ICH or sham surgery." (PMID 35242275, 2022). "The expression level of P38-mitogen-protein kinase (P38-MAPK), myeloid differentiation factor 88 (MyD88), high-mobility group box1 protein (HMGB1), and interleukin-1β (IL-1β) around hematoma was examined by western blotting at 24 h." (PMID 35242275, 2022). "In the present study, we clearly demonstrated that humanized anti-HMGB1 mAb not only inhibited inflammation, but also promoted hematoma clearance following ICH in marmosets." (PMID 36230933, 2022). "ICH elevated the expression of P38 MAPK, MyD88, HMGB1, and IL-1β around the hematoma when compared with sham surgery at 24 h after ICH or sham surgery (all p < 0.05)." (PMID 35242275, 2022). "In the present study, we clearly demonstrated that anti-HMGB1 mAb inhibited the deposition of hemosiderin and iron in the area surrounding the hematoma in ICH marmosets." (PMID 36230933, 2022). "HMGB1, defined as a cytokine rapidly released from the nucleus to the cytoplasm, promoted inflammatory response by activating microglia around the hematoma and aggravated brain injury after ICH in rats." (PMID 35242275, 2022). "We found that there were significant differences in the expression of P38 MAPK (F = 7.429, p = 0.002), MyD88 (F = 6.973, p = 0.002), HMGB1 (F = 11.753, p < 0.001), and IL-1β (F = 6.821, p = 0.002) around hematoma among the four groups (n = 6 mice/group)." (PMID 35242275, 2022). "Our results above demonstrated that the hematoma developed following ICH stimulated the production of HMGB1." (PMID 20936104, 2010). "Although the expression of P38 MAPK, HMGB1, and IL-1β around the hematoma increased slightly in mice that received a choline diet when compared with those of mice that received a regular diet at 24 h after ICH, the difference was not statistically significant (all p > 0.05)." (PMID 35242275, 2022). "In conclusion, our study revealed that acute intravenous injection of humanized an-ti-HMGB1 mAb produced a beneficial effect through the inhibition of the inflammatory responses, facilitation of the resolution of hematoma, and suppression of iron deposition after ICH." (PMID 36230933, 2022). "Nevertheless, it remained to be determined whether the hematoma developed following ICH could stimulate the generation of HMGB1 in the perihematomal brain tissue." (PMID 20936104, 2010). "Therefore, humanized anti-HMGB1 mAb could neutralize HMGB1 and liberate an abundant amount of haptoglobin to increase the clearance of Hb from hematoma clots." (PMID 36230933, 2022). "We observed that the humanized anti-HMGB1 mAb exerted both acute and long-lasting beneficial effects on marmoset ICH by reducing deleterious proinflammatory responses and promoting hematoma absorption." (PMID 36230933, 2022).
HIV-1 infection (5 papers, 2008 to 2025). The type species of lentivirus and the etiologic agent of acquired immunodeficiency syndrome (AIDS). "Circulating levels of HMGB1 are elevated during the course of HIV-1 infection and positively associated with high viral load." (PMID 26871575, 2016). "In the setting of HIV-1 infection, elevated plasma levels of HMGB1 were detected during progressive HIV-1 infection, positively associated with viral replication." (PMID 26871575, 2016). "Increased circulating HMGB1 levels detected in progressive HIV-1 infection, combined with microbial products (such as LPS) and TLR ligands, may contribute to gut inflammation and subsequent microbial translocation, suggested to have an important role in HIV pathogenesis." (PMID 26871575, 2016). "Altogether, these findings identify HMGB1 as a trigger for IFN-α-mediated TRAIL expression at the surface of pDCs and NK cells, and they suggest a novel mechanism of innate control of HIV-1 infection." (PMID 26871575, 2016). "In addition, HIV-1 infection induces NLRP3 inflammasome activation and elevated plasma high mobility group box 1 (HMGB1) levels." (PMID 31481891, 2019). "Strikingly, HIV-1 infection of iDC did not affect the amount of HMGB1 produced in NK-DC cocultures and in cultures of mature DCs." (PMID 18974890, 2008).
Infertility (5 papers, 2016 to 2025). "Although excessive inflammation often causes infertility, a physiological level of exogenous HMGB1 should be beneficial for mouse and human decidualization." (PMID 36761729, 2023). "In testes of infertile men and an autoimmune orchitis rat model, activation of HMGB1 signaling has been characterized." (PMID 35890148, 2022). "The Hmgb1 gene was found to be one of the 159 transcripts from testicular biopsy where the expression was found to be high in idiopathic infertile patients of AZFc microdeletion." (PMID 26963275, 2016). "The higher expression of Hmgb1 in neonatal (immature) testis of mice and testis of infertile patients, led us to hypothesize that higher expression of HMGB1can keep the testis in immature state whereas moderate expression is seen during spermatogenesis." (PMID 26963275, 2016). "Despite these insights, the role of HMGB-1 in infertility is unknown." (PMID 41226929, 2025). "This study showed increased HMGB-1 release, decreased steroidogenesis, and increased inflammation in granulosa cells after oxidative stress to explain the follicular environmental changes in patients with EMS and infertility." (PMID 41226929, 2025).
invasive breast carcinoma (5 papers, 2022 to 2025). A carcinoma that infiltrates the breast parenchyma. "In GSEA using Breast Invasive Carcinoma data (TCGA, Firehose Legacy), the ‘STAT3_02 gene set’ representing STAT3 target genes was enriched in patients with high HMGB1 expression compared to those with low HMGB1 expression." (PMID 40389855, 2025). "The significant associations between HMGB1 deficiency and dismal tumor phenotype in ccRCC, urothelial carcinoma, and invasive breast carcinomas of no special type (NST) argue for low HMGB1 expression levels, going along with aggressive cancer behavior at least in certain cancer entities." (PMID 40804938, 2025).
laryngeal squamous cell carcinoma (5 papers, 2019 to 2025). A squamous cell carcinoma that arises from the larynx. "The presence of HMGB1 in serum has been significantly correlated with poor prognosis in laryngeal squamous cell carcinoma." (PMID 37897664, 2024). "HMGB1+CD163+ M2 macrophages were found as detrimental prognostic factors for OS in laryngeal squamous cell carcinoma patients." (PMID 36686729, 2022). "In addition, H19 can regulate the expression of HMGB1 by targeting miR-107, demonstrating an inhibitory effect on autophagy both in vitro and in vivo, and enhance the sensitivity of laryngeal squamous cell carcinoma to cisplatin." (PMID 37897664, 2024). "HMGB1, CD163, and D2-40 in laryngeal squamous cell carcinoma (LSCC, n = 123), laryngeal precursor lesions (LPLs, n = 102), and vocal polyp (VP, n = 55) were analyzed by immunohistochemistry." (PMID 35280439, 2022).
limb ischemia (5 papers, 2019 to 2023). A ischemia that involves the limb. "HMGB-1 has been shown also to promote vascular endothelial growth factor (VEGF) dependent angiogenesis in animal models of limb ischemia, suggesting a role of HMGB-1 in tissue repair." (PMID 36244983, 2022). "In fact, in diabetic mice with experimental model of limb ischemia, HMGB1 levels are decreased in ischemic tissues; furthermore, administration of HMGB1 improves neovascularization via a VEGF-dependent mechanism." (PMID 31835864, 2019). "Interestingly, data by Xu and coworkers demonstrated that in mice with experimental limb ischemia, administration of chloroquine improves perfusion recovery and it induces HMGB1 release in sarcoplasm of muscle tissue and in serum." (PMID 31835864, 2019).
metastatic melanoma (5 papers, 2016 to 2024). A melanoma that has spread from its primary site to another anatomic site. "A study provided a new mechanistic link from UV-induced DNA damage of epidermal keratinocytes to metastatic melanoma, which was a series of events of UV exposure, HMGB1 release from damaged cells, HMGB1-TLR4-Myd88 signaling-mediated inflammation." (PMID 38786066, 2024). "In metastatic melanoma, serum HMGB1 levels in human patient samples have been shown elevated compared to healthy controls." (PMID 34209703, 2021). "To this end, we analysed HMGB1 levels in the serum of patients with primary melanoma, metastatic melanoma and in age-matched healthy volunteers." (PMID 27426915, 2016). "To determine if metastatic melanoma cells release HMGB1 in response to hypoxia, we analysed metastatic melanoma cell-lines grown in hypoxic versus normoxic conditions in vitro." (PMID 27426915, 2016). "Additionally, a murine model of metastatic melanoma analysis of dissociated tumors by flow cytometry showed a significant increase in the total number of TAMs exhibiting a M2 phenotype in HMGB1-positive tumors." (PMID 34209703, 2021). "Therefore, HMGB1 may contribute to the bystander effect induced by IL PV-10 in patients with metastatic melanoma." (PMID 27177220, 2016).
metastatic tumors (5 papers, 2011 to 2024). "The study showed that the high expression of HMGB1 increased the risk of metastatic disease with poor prognosis." (PMID 34445745, 2021). "Increased expression of RAGE and its ligand HMGB1 is usually observed in metastatic tumors and has been associated with invasion and poor prognosis." (PMID 21489226, 2011). "Acknowledging the small number when specifically examining those alive with metastatic disease at censoring (N = 6), it was still notable that the post-NACT HMGB1 was not maintained during the sequential CRT." (PMID 31893287, 2020).
osteoporosis (5 papers, 2020 to 2025). A condition of reduced bone mass, with decreased cortical thickness and a decrease in the number and size of the trabeculae of cancellous bone (but normal chemical composition), resulting in increased fracture incidence. "E3 ubiquitin ligase CUL4A promoted osteoclast differentiation and osteoporosis by upregulating ZEB1 to repress miR-340-5p expression, causing HMGB1 upregulation and the TLR4 activation." (PMID 38504994, 2024). "The keywords used were combined as follows: “alarmins and osteoporosis”, “RAGE and osteoporosis”, “HMGB1 and osteoporosis”, “IL-1 and osteoporosis”, “IL 33 and osteopororsis”, “S100s protein and osteoporosis”." (PMID 32204562, 2020). "Moreover, USP7 might contribute to osteoporosis, which enhanced osteoclast differentiation by deubiquitinating HMGB1." (PMID 40329406, 2025). "HMGB-1 knockout suppressed ovariectomy-evoked activation of the TLR4/NF-κB signaling cascade, resulting in the alleviation of osteoporosis." (PMID 38504994, 2024). "The results of their study showed that high mobility group box 1 (HMGB-1) knockout suppressed ovariectomy-evoked activation of the TLR4/NF-κB signaling cascade, resulting in the alleviation of osteoporosis." (PMID 38504994, 2024). "In particular, the receptor for advanced glycation end products (RAGE), whose role in bone homeostasis and osteoporosis is starting to be discovered, is a PRR binding several endogenous and exogenous ligands, including HMGB-1 and 2 and S100 proteins." (PMID 32204562, 2020).